HLA-DRB1 (major histocompatibility complex, class II, DR beta 1)
Description:
A beta chain of antigen-presenting major histocompatibility complex class II (MHCII) molecule. In complex with the alpha chain HLA-DRA, displays antigenic peptides on professional antigen presenting cells (APCs) for recognition by alpha-beta T cell receptor (TCR) on HLA-DRB1-restricted CD4-positive T cells. This guides antigen-specific T-helper effector functions, both antibody-mediated immune response and macrophage activation, to ultimately eliminate the infectious agents and transformed cells. Typically presents extracellular peptide antigens of 10 to 30 amino acids that arise from proteolysis of endocytosed antigens in lysosomes. In the tumor microenvironment, presents antigenic peptides that are primarily generated in tumor-resident APCs likely via phagocytosis of apoptotic tumor cells or macropinocytosis of secreted tumor proteins. Presents peptides derived from intracellular proteins that are trapped in autolysosomes after macroautophagy, a mechanism especially relevant for T cell selection in the thymus and central immune tolerance. The selection of the immunodominant epitopes follows two processing modes: 'bind first, cut/trim later' for pathogen-derived antigenic peptides and 'cut first, bind later' for autoantigens/self-peptides. The anchor residue at position 1 of the peptide N-terminus, usually a large hydrophobic residue, is essential for high affinity interaction with MHCII molecules. Allele DRB1*01:01: Displays an immunodominant epitope derived from Bacillus anthracis pagA/protective antigen, PA (KLPLYISNPNYKVNVYAVT), to both naive and PA-specific memory CD4-positive T cells. Presents immunodominant HIV-1 gag peptide (FRDYVDRFYKTLRAEQASQE) on infected dendritic cells for recognition by TRAV24-TRBV2 TCR on CD4-positive T cells and controls viral load. May present to T-helper 1 cells several HRV-16 epitopes derived from capsid proteins VP1 (PRFSLPFLSIASAYYMFYDG) and VP2 (PHQFINLRSNNSATLIVPYV), contributing to viral clearance. Displays commonly recognized peptides derived from IAV external protein HA (PKYVKQNTLKLAT and SNGNFIAPEYAYKIVK) and from internal proteins M, NP and PB1, with M-derived epitope (GLIYNRMGAVTTEV) being the most immunogenic. Presents a self-peptide derived from COL4A3 (GWISLWKGFSF) to TCR (TRAV14 biased) on CD4-positive, FOXP3-positive regulatory T cells and mediates immune tolerance to self. May present peptides derived from oncofetal trophoblast glycoprotein TPBG 5T4, known to be recognized by both T-helper 1 and regulatory T cells. Displays with low affinity a self-peptide derived from MBP (VHFFKNIVTPRTP). Allele DRB1*03:01: May present to T-helper 1 cells an HRV-16 epitope derived from capsid protein VP2 (NEKQPSDDNWLNFDGTLLGN), contributing to viral clearance. Displays self-peptides derived from retinal SAG (NRERRGIALDGKIKHE) and thyroid TG (LSSVVVDPSIRHFDV). Presents viral epitopes derived from HHV-6B gH/U48 and U85 antigens to polyfunctional CD4-positive T cells with cytotoxic activity implicated in control of HHV-6B infection. Presents several immunogenic epitopes derived from C.tetani neurotoxin tetX, playing a role in immune recognition and long-term protection. Allele DRB1*04:01: Presents an immunodominant bacterial epitope derived from M.tuberculosis esxB/culture filtrate antigen CFP-10 (EISTNIRQAGVQYSR), eliciting CD4-positive T cell effector functions such as IFNG production and cytotoxic activity. May present to T-helper 1 cells an HRV-16 epitope derived from capsid protein VP2 (NEKQPSDDNWLNFDGTLLGN), contributing to viral clearance. Presents tumor epitopes derived from melanoma-associated TYR antigen (QNILLSNAPLGPQFP and DYSYLQDSDPDSFQD), triggering CD4-positive T cell effector functions such as GMCSF production. Displays preferentially citrullinated self-peptides derived from VIM (GVYATR/citSSAVR and SAVRAR/citSSVPGVR) and ACAN (VVLLVATEGR/ CitVRVNSAYQDK). Displays self-peptides derived from COL2A1. Allele DRB1*04:02: Displays native or citrullinated self-peptides derived from VIM. Allele DRB1*04:04: May present to T-helper 1 cells several HRV-16 epitopes derived from capsid proteins VP1 (HIVMQYMYVPPGAPIPTTRN) and VP2 (RGDSTITSQDVANAVVGYGV), contributing to viral clearance. Displays preferentially citrullinated self-peptides derived from VIM (SAVRAR/citSSVPGVR). Allele DRB1*04:05: May present to T-helper 1 cells an immunogenic epitope derived from tumor-associated antigen WT1 (KRYFKLSHLQMHSRKH), likely providing for effective antitumor immunity in a wide range of solid and hematological malignancies. Allele DRB1*05:01: Presents an immunodominant HIV-1 gag peptide (FRDYVDRFYKTLRAEQASQE) on infected dendritic cells for recognition by TRAV24-TRBV2 TCR on CD4-positive T cells and controls viral load. Allele DRB1*07:01: Upon EBV infection, presents latent antigen EBNA2 peptide (PRSPTVFYNIPPMPLPPSQL) to CD4-positive T cells, driving oligoclonal expansion and selection of a dominant virus-specific memory T cell subset with cytotoxic potential to directly eliminate virus-infected B cells. May present to T-helper 1 cells several HRV-16 epitopes derived from capsid proteins VP1 (PRFSLPFLSIASAYYMFYDG) and VP2 (VPYVNAVPMDSMVRHNNWSL), contributing to viral clearance. In the context of tumor immunesurveillance, may present to T-helper 1 cells an immunogenic epitope derived from tumor-associated antigen WT1 (MTEYKLVVVGAVGVGKSALTIQLI), likely providing for effective antitumor immunity in a wide range of solid and hematological malignancies. In metastatic epithelial tumors, presents to intratumoral CD4-positive T cells a KRAS neoantigen (MTEYKLVVVGAVGVGKSALTIQLI) carrying G12V hotspot driver mutation and may mediate tumor regression. Allele DRB1*11:01: Displays an immunodominant HIV-1 gag peptide (FRDYVDRFYKTLRAEQASQE) on infected dendritic cells for recognition by TRAV24-TRBV2 TCR on CD4-positive T cells and controls viral load. May present to T-helper 1 cells an HRV-16 epitope derived from capsid protein VP2 (SDRIIQITRGDSTITSQDVA), contributing to viral clearance. Presents several immunogenic epitopes derived from C.tetani neurotoxin tetX, playing a role in immune recognition and longterm protection. In the context of tumor immunesurveillance, may present tumor-derived neoantigens to CD4-positive T cells and trigger anti-tumor helper functions. Allele DRB1*13:01: Presents viral epitopes derived from HHV-6B antigens to polyfunctional CD4-positive T cells implicated in control of HHV-6B infection. Allele DRB1*15:01: May present to T-helper 1 cells an HRV-16 epitope derived from capsid protein VP2 (SNNSATLIVPYVNAVPMDSM), contributing to viral clearance. Displays a self-peptide derived from MBP (ENPVVHFFKNIVTPR). May present to T-helper 1 cells an immunogenic epitope derived from tumor-associated antigen WT1 (KRYFKLSHLQMHSRKH), likely providing for effective antitumor immunity in a wide range of solid and hematological malignancies. Allele DRB1*15:02: Displays an immunodominant HIV-1 gag peptide (FRDYVDRFYKTLRAEQASQE) on infected dendritic cells for recognition by TRAV24-TRBV2 TCR on CD4-positive T cells and controls viral load. May present to T-helper 1 cells an immunogenic epitope derived from tumor-associated antigen WT1 (KRYFKLSHLQMHSRKH), likely providing for effective antitumor immunity in a wide range of solid and hematological malignancies. (Microbial infection) Acts as a receptor for Epstein-Barr virus on lymphocytes.
Synonyms: DRB1; HLA-DR1B; HLA-DRB; SS1
Tractability: Small molecule: a drug acting on it is in phase 2 or 3 trials; a structure with a bound ligand is known. Antibody: a drug acting on it is in phase 2 or 3 trials; UniProt places it where antibodies can reach, with high confidence; its Gene Ontology location is reachable by antibodies, with high confidence; UniProt predicts a signal peptide or a membrane-spanning region. PROTAC: UniProt records ubiquitination sites on it; ubiquitination databases record sites on it; a small molecule that binds it is known.
Target class: Surface antigen
Safety:
Unwanted effects reported when the protein is acted on. In parentheses: how it was acted on, where the effect was seen, and who reports it.
agranulocytosis (source: ClinPGx)
anaphylactoid reaction (source: ClinPGx)
dapsone hypersensitivity (source: ClinPGx)
DRESS Syndrome or SJS/TEN (source: ClinPGx)
hypersensitivity (source: ClinPGx)
hypersensitivity reactions (source: ClinPGx)
hypersensitivity to asparaginase (source: ClinPGx)
hypersensitivity to dapsone (source: ClinPGx)
lapatinib-induced liver injury (source: ClinPGx)
liver injury (source: ClinPGx)
maculopapular eruption (source: ClinPGx)
maculopapular eruption (MPE) (source: ClinPGx)
maculopapular eruption when treated with carbamazepine (source: ClinPGx)
nevirapine-induced adverse reactions (source: ClinPGx)
pancreatitis (source: ClinPGx)
Pegaspargase Hypersensitivity (source: ClinPGx)
severe cutaneous adverse reactions (source: ClinPGx)
severe cutaneous adverse reactions (SCAR) (source: ClinPGx)
statin-related myopathy (source: ClinPGx)
toxic liver disease (source: ClinPGx)
Gene: Protein-coding gene on chromosome 6 (32,577,902 to 32,589,848, reverse strand). Ensembl gene ENSG00000196126.
Subcellular location: Cell membrane; Endoplasmic reticulum membrane; Lysosome membrane; Late endosome membrane; Autolysosome membrane
Pathways (Reactome):
Immune System: Co-inhibition by PD-1; Downstream TCR signaling; Generation of second messenger molecules; Interferon gamma signaling; MHC class II antigen presentation; Phosphorylation of CD3 and TCR zeta chains; Translocation of ZAP-70 to Immunological synapse
Gene Ontology:
Molecular function: CD4 receptor binding; MHC class II protein complex binding; peptide antigen binding; polysaccharide binding; protein binding; T cell receptor binding; structural constituent of cytoskeleton
Biological process: antigen processing and presentation of endogenous peptide antigen via MHC class II; antigen processing and presentation of exogenous peptide antigen via MHC class II; detection of bacterium; humoral immune response; immune response; inflammatory response to antigenic stimulus; macrophage differentiation; myeloid dendritic cell antigen processing and presentation; negative regulation of inflammatory response to antigenic stimulus; negative regulation of T cell proliferation; negative regulation of type II interferon production; peptide antigen assembly with MHC class II protein complex; positive regulation of CD4-positive, alpha-beta T cell activation; positive regulation of CD4-positive, CD25-positive, alpha-beta regulatory T cell differentiation; positive regulation of insulin secretion involved in cellular response to glucose stimulus; positive regulation of memory T cell differentiation; positive regulation of monocyte differentiation; positive regulation of T cell mediated cytotoxicity; positive regulation of T cell mediated immune response to tumor cell; protein tetramerization; regulation of interleukin-10 production; regulation of interleukin-4 production; regulation of T-helper cell differentiation; signal transduction; T cell receptor signaling pathway; and 6 more
Cellular component: autolysosome membrane; cell surface; endoplasmic reticulum membrane; external side of plasma membrane; extracellular exosome; extracellular region; immunological synapse; late endosome membrane; lysosomal membrane; membrane; MHC class II protein complex; plasma membrane; clathrin-coated endocytic vesicle membrane; endocytic vesicle membrane; ER to Golgi transport vesicle membrane; Golgi membrane; intermediate filament; lumenal side of endoplasmic reticulum membrane; trans-Golgi network membrane; transport vesicle membrane
Genetic constraint (gnomAD): Loss-of-function variants: 6 observed, 4.81 expected, observed/expected ratio (o/e) 1.25, 90% interval 0.66 to 1.89. That is too few expected variants to judge how well the gene tolerates losing a copy. Missense variants: 61 observed, 64.59 expected, observed/expected ratio (o/e) 0.94, 90% interval 0.77 to 1.17. Synonymous variants: 31 observed, 25.76 expected, observed/expected ratio (o/e) 1.2, 90% interval 0.9 to 1.62.
Homologues: Orthologues: chimpanzee PATR-DQB1 (91% identical), mouse H2-Eb2 (64% identical). Paralogues in human: HLA-DRB5 (89% identical), HLA-DQB2 (64% identical), HLA-DQB1 (62% identical), HLA-DPB1 (61% identical), HLA-DOB (55% identical), HLA-DQA1 (22% identical), HLA-DQA2 (22% identical), HLA-DOA (21% identical), HLA-DRA (21% identical), HLA-DMB (21% identical), HLA-DPA1 (21% identical), HLA-DMA (19% identical), and 1 more.
Diseases named in the same sentence as HLA-DRB1 in open-access papers:
HLA-DRB1 is named in the same sentence as 422 diseases in open-access papers, as found by Europe PMC text mining. Sharing a sentence is not in itself a finding about the gene and the disease. The quoted sentences say what the papers report.
rheumatoid arthritis (219 papers, 2005 to 2026). A chronic, systemic autoimmune disorder characterized by inflammation in the synovial membranes and articular surfaces. "Among the genetic risk factors associated with rheumatoid arthritis, the HLA-DRB1*1402 antigen is a distinctive allele that encodes shared epitopes and is found to be prevalent in indigenous native peoples in the US." (PMID 41300642, 2025). "For example, HLA-DRB1*04:01, 04:04, 04:05, and 01:01 alleles are associated with susceptibility to rheumatoid arthritis." (PMID 41009363, 2025). "Comparison of frequencies of a subset of HLA-A*, HLA-B* and HLA-DRB1* alleles between patients with rheumatoid arthritis and the Croatian population of bone marrow donors." (PMID 41325321, 2025). "For example, HLA-DRB1 variants are linked to rheumatoid arthritis (RA), and HLA-DR3 and HLA-DR4 significantly increase the risk for type 1 diabetes (T1D)." (PMID 40852720, 2025). "Meta-analysis SNP rs679242 (6p21.32; HLA-DRB1) has been previously significantly associated with several diseases including rheumatoid arthritis (p=1.1×10−121), type 1 diabetes (p=4.6×10−63), and type 2 diabetes (p=2.8×10−14)." (PMID 40666354, 2025). "Rheumatoid Arthritis (RA) is an autoimmune disease in which HLA-DRB1 alleles encoding the “Shared Epitope” (SE), located in the β-chain of class II HLA-DR molecules, constitute the main genetic risk factor." (PMID 41444678, 2025). "HLA-DRB1 is associated with several autoimmune and autoinflammatory disorders, most notably rheumatoid arthritis (RA)." (PMID 40666354, 2025). "The dysfunction of HLA-DMA can cause immunodeficiency and autoimmune diseases, and HLA-DRB1 has been reported to be associated with the risk of GD and rheumatoid arthritis." (PMID 40710355, 2025). "Specific HLA alleles include HLA-DR3 and HLA-DR4 (associated with type 1 diabetes—T1D), as well as HLA-DRB1 (associated with rheumatoid arthritis—RA and multiple sclerosis—MS), HLA-DQB1 (associated with MS), and HLA-B27 (associated with AS)." (PMID 40507438, 2025). "In the existing literature, HLA-DRB1*04:05 has been extensively linked to autoimmune diseases, including rheumatoid arthritis (RA) and autoimmune hepatitis (AIH)." (PMID 40141400, 2025). "For instance, the human leukocyte antigen-DRB1 (HLA-DRB1) gene is strongly associated with susceptibility to rheumatoid arthritis (RA), and certain HLA-DQ and HLA-DR alleles offer protection against type 1 diabetes." (PMID 39062908, 2024). "Genetic studies have shown that certain HLA-DRB1 alleles, particularly the rheumatoid arthritis (RA)-shared epitope, are associated with a higher likelihood of relapses." (PMID 39518631, 2024). "CD4+ T cells recognising citrullinated self-epitopes presented by HLA-DRB1 bearing the shared susceptibility epitope (SE) are implicated in rheumatoid arthritis (RA)." (PMID 39043656, 2024). "CD4+ T cells recognising shared susceptibility epitope (SE) encoded HLA-DRB1 presenting citrullinated self-peptides are implicated in rheumatoid arthritis." (PMID 39043656, 2024). "The association between periodontitis and the pathologic outcomes of rheumatoid arthritis is linked to the specific alleles in the highly polymorphic HLA-DRB1 locus." (PMID 37190018, 2023). "HLA-DRB1*01, *04, and *10 alleles have shown a very strong genetic risk factor for the development of rheumatoid arthritis." (PMID 38021518, 2023). "Family history for rheumatoid arthritis is positive in approximately 40% of FS patients and HLA-DRB1 alleles are identified in up to 90% of FS cases." (PMID 37920595, 2023). "In for instance Colombian patients with systemic lupus erythematosus and German patients with rheumatoid arthritis, PB lymphopenia was associated with specific HLA-DRB1 alleles." (PMID 37161980, 2023). "For example, HLA-DRB1 seems to predispose to development of rheumatoid arthritis inducing the selection of autoreactive CD4 + T cells which can be intriguingly found in both synovial tissue and atherosclerotic plaque." (PMID 37219757, 2023).